SGCZ (sarcoglycan zeta)
Description:
Component of the sarcoglycan complex, a subcomplex of the dystrophin-glycoprotein complex which forms a link between the F-actin cytoskeleton and the extracellular matrix. May play a role in the maintenance of striated muscle membrane stability (By similarity).
Synonyms: ZSG1
Tractability: Antibody: its Gene Ontology location is reachable by antibodies, with high confidence; UniProt places it where antibodies can reach, with medium confidence; UniProt predicts a signal peptide or a membrane-spanning region.
Gene: Protein-coding gene on chromosome 8 (14,084,845 to 15,238,431, reverse strand). Ensembl gene ENSG00000185053.
Subcellular location: Cell membrane, sarcolemma; Cytoplasm, cytoskeleton
Pathways (Reactome):
Extracellular matrix organization: Formation of the dystrophin-glycoprotein complex (DGC)
Gene Ontology:
Biological process: cardiac muscle tissue development; heart contraction; membrane organization; muscle cell cellular homeostasis; muscle cell development; synaptic signaling
Cellular component: dystrophin-associated glycoprotein complex; endoplasmic reticulum membrane; Golgi membrane; plasma membrane; sarcoglycan complex; sarcolemma; cytoskeleton; membrane; synapse
Genetic constraint (gnomAD): Loss-of-function variants: 35 observed, 34.85 expected, observed/expected ratio (o/e) 1, 90% interval 0.77 to 1.33. The synonymous counts are far from expectation, so gnomAD's model fits this gene poorly and the ratio says little. Missense variants: 523 observed, 333.22 expected, observed/expected ratio (o/e) 1.57, 90% interval 1.46 to 1.69. Synonymous variants: 193 observed, 125.65 expected, observed/expected ratio (o/e) 1.54, 90% interval 1.37 to 1.73.
Homologues: Orthologues: chimpanzee SGCZ (100% identical), macaque SGCZ (99% identical), pig SGCZ (97% identical), rabbit SGCZ (97% identical), dog SGCZ (96% identical), rat Sgcz (96% identical), guinea pig SGCZ (95% identical), mouse Sgcz (95% identical), tropical clawed frog sgcz (79% identical), zebrafish SGCZ (71% identical), Drosophila melanogaster Scgdelta (37% identical), Caenorhabditis elegans sgn-1 (33% identical). Paralogues in human: SGCG (54% identical), SGCD (54% identical).
Diseases named in the same sentence as SGCZ in open-access papers:
SGCZ is named in the same sentence as 30 diseases in open-access papers, as found by Europe PMC text mining. Sharing a sentence is not in itself a finding about the gene and the disease. The quoted sentences say what the papers report.
Obesity (3 papers, 2013 to 2022). Accumulation of substantial excess body fat. "The SGCZ gene has been reported in genome-wide association studies (GWAS) of BMI and obesity-related traits." (PMID 35769078, 2022). "Further, CNVs in both SGCZ and PARK2 have also been associated with obesity-related traits in African Americans suggesting that these two genes function in a concerted manner." (PMID 25083881, 2014).
breast carcinoma (2 papers, 2012 to 2017). "Among these, 11 CNVRs overlapped with 12 genes (GSTM2, RAB40B, HLA_DRB5, HLA_DRB6, EYA1, DOCK3, ANKS1B, CACNA1C, RAB11FIP3, BAGE, SGCZ, POM121c) and were specifically associated with breast cancer risk and OS." (PMID 29116104, 2017). "A link between SGCZ, KIAA1456 or C8orf48 and breast cancer has not been established, however, DLC1 has been shown to inhibit cancer cell growth and been implicated as a tumor suppressor." (PMID 23056464, 2012).
prediabetes (2 papers, 2022 to 2025). "Despite biologically relevant in diabetes development, our study provided the first evidence that the SGCZ gene is involved in prediabetes status change in humans." (PMID 35769078, 2022).
aneurysm (1 paper, 2019). Bulging or ballooning in an area of an artery secondary to arterial wall weakening. "Although none of the SNPs reached a genome-wide significance threshold for IA rupture, one intron variant, the rs6990241 of the SGCZ gene (8p22), showed a suggestive association with aneurysm rupture (OR = 0.34, 95% CI 0.22-0.55; p = 8.5 × 10−6)." (PMID 30823506, 2019).
choroidal neovascularization (1 paper, 2025). An eye disorder described by the growth of new blood vessels that originate from the choroid through a break in the Bruch membrane into the sub–retinal pigment epithelium (sub-RPE) or subretinal space. "However, further investigation is needed to understand how SGCZ may be related to the response to anti-VEGF therapy in retinal conditions with macular edema, particular as BCVA loss is a functional indirect effect of VEGF-induced ME and choroidal neovascularization." (PMID 40455044, 2025).
diabetes (1 paper, 2022). "Animal studies have provided further evidence for the involvement of the SGCZ gene in diabetes development." (PMID 35769078, 2022).
glaucoma (1 paper, 2025). Increased pressure in the eyeball due to obstruction of the outflow of aqueous humor. "Second, we identified an intronic variant in the SGCZ gene on chromosome 8 that has previously been linked to BMI 65, reinforcing the possible role of metabolic pathways in glaucoma development." (PMID 41282083, 2025).
hemochromatosis (1 paper, 2017). A disorder of iron metabolism characterized by a triad of HEMOSIDEROSIS; LIVER CIRRHOSIS; and DIABETES MELLITUS. "rs9393682 is located in the intergenic region between HIST1H1C (histone cluster 1 H1 family member c) and HFE (hemochromatosis), and rs1378033 is located in the intron of SGCZ (sarcoglycan zeta) and 5′ of TUSC3 (tumor suppressor candidate 3)." (PMID 29088772, 2017).
pancreatic cancers (1 paper, 2023). "miRNA-143-5p has been implicated in the pathophysiology of cancer (including colon and pancreatic cancers) and schizophrenia-related disorders, and its effects on various target genes, such as EMC2, VWC2L, THY1, SGCZ, HIF1, and JDP2, among others, have been described." (PMID 37179125, 2023).
prostate carcinoma (1 paper, 2017). A carcinoma that arises from epithelial cells of the prostate gland. "The effects of 1,25-VD on the mRNA expression levels of HIST1H1C, HFE, SGCZ, TUSC3, and CYP24A1 (cytochrome P450 family 24 subfamily A member 1), a well-known 1,25-VD target gene, were examined using quantitative real-time polymerase chain reaction (qRT-PCR) in PC-3 human prostate cancer cells." (PMID 29088772, 2017).
salivary gland cancer (1 paper, 2024). A primary or metastatic malignant neoplasm that affects the major or minor salivary glands. "The patient with NSCLC harbored an SGCZ::NTRK3 fusion tumor, while the patient with salivary gland cancer harbored an ETV6::NTRK3 fusion." (PMID 38967220, 2024). "Other detected fusions were SGCZ::NTRK3 (NSCLC) and ETV6::NTRK3 (salivary gland cancer)." (PMID 38967220, 2024).
cancer (5 papers, 2008 to 2025). A tumor composed of atypical neoplastic, often pleomorphic cells that invade other tissues. "Similarly, seven genes (SGCZ, KANK1, KDM4C, KCNMA1, ZNF263, CDH4, NCAM2) contain partial CNV duplications in both BD‐cancer and BD‐only patients, but the deleted loci are different." (PMID 39140252, 2025).
SGCZ also shares sentences with these, for which no sentence is quoted: tumor (3 papers); muscular dystrophy (2); schizophrenia (2); Aphasia (1); Autoimmunity (1); chronic pancreatitis (1); colon adenocarcinoma (1); dilated cardiomyopathy (1); endometriosis (1); epilepsy (1); gallstones (1); Intellectual disability (1); limb-girdle muscular dystrophy (1); macular edema (1); major depression (1); myoclonic dystonia (1); neurodegenerative disease (1); substance abuse (1).